RN7SL333P (RNA, 7SL, cytoplasmic 333, pseudogene)
Gene: Miscellaneous RNA gene on chromosome 1 (169,859,756 to 169,860,052, forward strand). Ensembl gene ENSG00000239494.
Homologues: Orthologues: chimpanzee Metazoa_SRP (99% identical), macaque Metazoa_SRP (92% identical), rabbit Metazoa_SRP (64% identical). Paralogues in human: RN7SL1 (85% identical), RN7SL2 (85% identical), RN7SL3 (84% identical), RN7SL122P (82% identical), RN7SL220P (82% identical), RN7SL126P (82% identical), RN7SL83P (82% identical), RN7SL45P (81% identical), RN7SL709P (81% identical), Metazoa_SRP (81% identical), RN7SL344P (81% identical), RN7SL630P (81% identical), and 702 more.